IL5 (interleukin 5)
Diseases named in the same sentence as IL5 in open-access papers (continued):
Sharing a sentence is not in itself a finding about the gene and the disease.
asthma (continued). "Type 2 airway inflammation induced by antigen-specific immunoglobulin E (IgE), interleukin-4 (IL-4), IL-5, IL-13, and thymic stromal lymphopoietin is associated with increased exacerbations and airway remodeling in patients with asthma." (PMID 35756113, 2022). "Hoverer, asthma comorbid AR patients showed an increase in the expression of systemic cytokine (IL-4, IL-5, and IL-25) in plasma; this was associated with a lower quality of life than that of patients with asthma." (PMID 35348596, 2022). "Kleiner at al. reported undetectable levels of IL-5 in serum of healthy subjects, however, this cytokine was associated with the pathophysiology of asthma." (PMID 36211483, 2022). "IL-5 has been reported to be associated with several allergic diseases including asthma and allergic rhinitis, which were risk factors for developing OSA." (PMID 35967324, 2022). "Among these cytokines, IL-4 and IL-5 are mainly implicated in cardinal features of asthma, maturation of eosinophils and goblet cell, IgE mediated hypersensitive response, mucus secretion, bronchial constriction, and tissue remodeling." (PMID 38143476, 2022). "Next, Elevated serum total IgE levels, as marker for asthma, was obviously decreased in sTSLP group, as well as levels of Th2-associated cytokines (IL-4, IL-5 and IL-13) in the BALF of mice." (PMID 35351157, 2022). "Previous studies firstly focused on anti-IgE and anti-IL-5 therapies to treat EOM in association with asthma and/or CRSwNP." (PMID 35207196, 2022). "Asthma has been associated with T helper cell 2 (Th2)-mediated immunity due to aberrant production of IL-4, IL5, and IL13." (PMID 33914833, 2021). "In patients with associated asthma, IL-9 together with IL-5 induces IL-5Rα expression in airway eosinophils and promotes the anti-apoptotic action of IL-5." (PMID 35008843, 2021). "The pathogenic mechanisms of AD are similar to asthma, as they are both Th2-driven diseases with the enhancement of IL-4, IL-5, and IL-13 cytokines that can induce eosinophils and IgE recruitment." (PMID 34572281, 2021). "Cytokines commonly associated with eosinophilic inflammation in asthma include IL-3, IL-5, eotaxin, and GM-CSF." (PMID 35387066, 2021). "In an experimental asthma model, vitamin A deficiency in mice also worsened the inflammatory condition by increasing the Th2 cytokines IL-5 and IL-13 and pulmonary inflammation." (PMID 34557509, 2021). "ILC2s are important sources of Th2 cytokines such as IL-5 and IL-13 that contribute to the increased Th2-associated airway inflammation observed in asthma." (PMID 34101619, 2021). "Targeting type 2 inflammation via interleukin-5 inhibition has been associated with clinical benefits in patients with asthma and upper airway comorbidities." (PMID 34098955, 2021). "Hypomethylation of IL5RA (3p26.2) in the blood is associated with asthma in teens, and IL-5 plays a crucial role in eosinophilopoiesis." (PMID 34566492, 2021). "In asthma pathogenesis, the overexpression of several type 2 inflammatory mediators including IgE, IL-4, IL-5, IL-13, and TSLP has been associated with ASM hyperreactivity, all of which can be targeted by humanized monoclonal antibodies (mAbs)." (PMID 34572466, 2021). "Reports shows that adolescents with asthma who experienced more stress have higher levels of interleukin 5 (IL-5) and interferon-c (IFN-c), which associated with type 2 and type 1 immune responses, respectively." (PMID 34193097, 2021). "As asthma associated with CRSwNP is highly eosinophilic, anti-leukotriene (Montelukast), anti-IgE (Omalizumab) and anti IL-5 (Mepolizumab and reslizumab) treatments have shown promising results for both asthma and polyposis-sinus." (PMID 34123375, 2021). "Combined with our data showing TL1A is upstream of IL13, this indicates that targeting TL1A signaling offers an advantage over targeting IL13/IL4Rα or IL5 signaling in isolation to treat mucus secretion associated with asthma." (PMID 34305924, 2021).
asthma (continued). "Type 2 (T2)-high asthma is associated with elevated levels of Th2 cytokines such as IL-4, IL-5 and IL-13 whereas T2-low asthma is mainly linked to the activation of Th1 and Th17 cells." (PMID 34777398, 2021). "Global integration using Spearman correlation for all asthma phenotypes with the 17 microbial genera revealed that ten microbial genera were associated with the asthma phenotypes, except IL-5 levels." (PMID 32315360, 2020). "In particular, besides the downstream effectors of type 2 airway inflammation such as IgE, IL-5, IL-4/13 and their receptors, other very interesting pathogenic molecules include upstream activators of cellular pathways leading to T2-high asthma." (PMID 33329598, 2020). "The main cells associated with type 2- (T2-) high 2 asthma are eosinophils, due to the participation in the formation of various inflammatory mediators: IL-13, IL-5, chemokines, and cysteinyl leukotrienes, which are the powerful bronchoconstrictors." (PMID 32395125, 2020). "In CRS, IL-5 expression is a signature immune endotype, often associated with concurrent asthma or nasal polyps." (PMID 33014894, 2020). "The inflammation caused by asthma is originated from Th2 lymphocytes, which secrete a group of cytokines including IL-5, IL-4, IL-3, IL-13 and GM-CSF." (PMID 32489374, 2020). "Despite the glucocorticoid therapies have a great effect on maintaining the balance of Th1/Th2 in asthma, more studies have paid attention to various treatments targeting Th2-associated IL-4, IL-5, or IL-13." (PMID 33013382, 2020). "Eosinophilia during asthma development is associated with pro-inflammatory cytokines such as IL-4, IL-5 and IL-13." (PMID 31991647, 2020). "Where asthma and the common cold are directly linked to Interferon-gamma (IFNg), IL-8, IL-2 and IL-5, diarrhea is linked to IL-18." (PMID 32746922, 2020). "Elevated bronchial expression of IL-5 and IL-13 has been shown to be associated with sputum and blood eosinophilia and moderate-to-severe asthma." (PMID 33322143, 2020). "While IL-5-mediated eosinophilic inflammation has been clearly demonstrated in certain asthma phenotypes, IL-5- and eosinophil-associated inflammation is less apparent in IgE-mediated food allergies." (PMID 33224138, 2020). "Anti-inflammatory activity of GMP in experimental asthma and atopic dermatitis has also been associated with decreased levels of IL-5 and IL-13 in affected tissues." (PMID 32992996, 2020). "On the other hand, asthma, a risk factor for adverse outcomes in COVID-19, is linked to IL-8, IL-5, IL-2, IFNg, eosinophils, and neutrophils." (PMID 32746922, 2020). "For all such reasons, in severe T2-high asthma, IL-5 represents a pivotal pathogenic factor and a highly valuable target for add-on biological therapies of corticosteroid-resistant, difficult-to-treat eosinophilic phenotypes." (PMID 31920718, 2019). "The close pathogenic link between IL-5 and eosinophilic inflammation has been clearly demonstrated using both animal and human experimental models of asthma." (PMID 31920718, 2019). "AAL(S) was shown to reduce the severity in asthma mice models by suppressing inflammation, mucus-secreting cell numbers, type 2-associated cytokines (IL-33, IL-5 and IL-13), serum IgE and airway hyper-responsiveness." (PMID 31623614, 2019). "Many studies have shown that Th2 cells in the lungs of asthma patients release excessive IL-5, causing differentiation of bone marrow cells to mature eosinophils." (PMID 31226782, 2019). "In contrast, obese asthma in adults is associated with increased airway and systemic inflammation, consistent with our observations of increased TNFα, IL-5, IL-33 and leptin concentrations in the BALF of dams fed the high fat diet." (PMID 30700289, 2019). "Aberrant production of the Th2 and Th17 cytokines, IL-4, IL-5, IL-13, and IL-17, mediate the induction of the IgE isotype switch, which has long been associated with the pathogenesis of asthma." (PMID 30873032, 2019).
asthma (continued). "In the context of asthma associated with Th2 responses, it is possible that recruited NK cells will produce IL-4, IL-5, and IL-13 over IFN-γ, contributing therefore to both the pathology of asthma and impaired antiviral responses." (PMID 31167464, 2019). "The absence, or reduced concentration of IL-10, associated with asthma enables the continued secretion of pro-inflammatory cytokines that contribute to lower airway inflammation, including IL-6, IL-5, IL-4, TNF-α, and IL-1." (PMID 31694631, 2019). "With regard to the pathobiology of asthma, in addition to promoting the development and amplification of eosinophilic inflammation, IL-5 is also implicated in the induction of airway remodeling." (PMID 31920718, 2019). "Asthma is a T helper type 2 (Th2) cell-mediated eosinophilic inflammatory disease, and Th2 cytokines IL-4, IL-5, and IL-13 have been implicated in asthma pathology." (PMID 31852931, 2019). "Asthma is generally associated with Th2 cells, which produce a panel of cytokines (IL-4, IL-5, IL-13) that act in synergy to drive lung inflammatory responses, mucus secretion, IgE production, and fibrosis, causing the characteristic symptoms of asthma." (PMID 30105031, 2018). "This article discusses the different roles of the IgE and IL-5/eosinophil pathways in the pathogenic mechanisms of airway inflammation occurring in asthma, shedding light on the parts played by each in the induction and maintenance of the inflammatory process." (PMID 29879991, 2018). "A previous study revealed that the high concentration of IL-5 in the peripheral blood was also associated with the increase of exacerbation frequency in children with asthma." (PMID 30210646, 2018). "Most patients with asthma have an eosinophilic infiltration of the airways, associated with increased production of type 2 cytokines including IL-4, IL-5, IL-13 secreted by Th2 cells, together with allergic comorbidities." (PMID 30105031, 2018). "The pathological features of asthma are thought to be a consequence of the activation of Th2 cells and their associated cytokines including IL-4, IL-5, IL-9, and IL-13." (PMID 29922162, 2018). "The first IL-5 antibody mepolizumab has been approved for over two years and has since become an established therapy for patients with uncontrolled severe asthma caused mainly by type 2 inflammation." (PMID 30021546, 2018). "This myofibroblast marker is overexpressed in asthma, and its deficiency in animal models of asthma was shown to attenuate airway inflammation and, in particular, eosinophilia, IL-5 and IL-13 levels in BALF." (PMID 30101406, 2018). "Recent evidence indicates that Th2 cytokines (such as IL-5 and IL-13) and other T-cell associated cytokines (such as IL-22 and IL-17A) are involved in allergic airway inflammation in asthma." (PMID 29922162, 2018). "TH2 cells mainly secrete the cytokines IL-4, IL-5, and IL-13 to mediate inflammatory and remodeling changes in the airway mucosa that predispose an individual to asthma and to asthma exacerbations." (PMID 29951106, 2018). "A number of novel treatments for severe asthma are under development, some of which have been approved for clinical use: treatment with anti-IgE and anti-IL5 monoclonal antibodies are effective in reducing the risk of asthma exacerbations." (PMID 29535852, 2018). "Proteins associated to asthma and eczema are all related to immunity (IL1ß, IL5, IL33, C-C motif chemokine 5, eotaxin)." (PMID 28598986, 2017). "But a recent study showed that B7-H3 deficient mice developed severe OVA-induced asthma with characteristic infiltrations of eosinophils in the lung, increased IL-5 and IL-13 in lavage fluid, which suggests B7-H3 has a coinhibitory function on Th2 responses." (PMID 28094276, 2017). "T2-associated asthma is characterized by the release of interleukins IL-13 and IL-5, promoting eosinophilic infiltration, pro-inflammatory loops, epithelial cell proliferation, goblet-cell metaplasia, and ciliary beating alterations." (PMID 28303134, 2017).
asthma (continued). "Mixed responses characterized by IL-5 and IL-17 upregulation were associated with Difficult-to-Control disease while IL-4 and IL-13 were associated with Easy-to-Control asthma." (PMID 28686637, 2017). "We found an association between IL-17 and IL-5 with difficult-to-control asthma, in comparison to previous studies which report IL-4+IL-17+ or IL-13IL-17+ T-cell populations." (PMID 28686637, 2017). "Given the association of IL-17A and IL-5 with Difficult-to-Control asthma in African American children in our inner-city population, therapeutics targeting IL-17 and IL-5 should be considered." (PMID 28686637, 2017). "A more detailed analysis of the immunological mechanisms underlying the pathogenesis of asthma shows interleukin 5 (IL-5) to be a crucial cytokine in several asthma phenotypes." (PMID 28913336, 2017). "CXCL-1, IL-5, IL-8, and IL-17A were positively associated with Difficult-to-Control asthma, while IL-4 and IL-13 were positively associated with Easy-to-Control asthma." (PMID 28686637, 2017). "IL-1RA was positively associated with Difficult-to-Control disease and IL-5 was positively associated with Easy-to-Control asthma." (PMID 28686637, 2017). "MMP1, MMP3, MMP8, and MMP12 levels were associated with severe asthma and were correlated positively with sputum IL-5 levels but negatively with IL-13 levels." (PMID 26851968, 2016). "For example, among youth with asthma, more chronic family and household stress is associated with increased production of the Th2 cytokines IL-5 and IL-13, and higher eosinophil counts." (PMID 27965775, 2016). "Asthma is a prevalent disease of chronic inflammation in which the Th2 cytokines IL-4, IL-5, and IL-13 are all tightly linked to the pathogenesis of asthma." (PMID 27547445, 2016). "In asthmatic patients, allergen challenge initiates the influx of TH2 cells in the airways leading to an increased production of TH2-associated cytokines including IL-4, IL-5, and IL-13 which promote the detrimental inflammation associated with asthma." (PMID 27378934, 2016). "Unlike other inflammatory diseases, the inflammatory response in asthma is associated with increased T help (Th) 2 cytokine production from T lymphocyte infiltration, including interleukin (IL)-4, IL-5 and IL-131." (PMID 26956917, 2016). "Th2 cells produce high level of IL-4, IL-5 and IL-13 which are closely associated with asthma symptoms." (PMID 27870920, 2016). "Th2-type cytokines (such as IL-4, IL-5, and IL-13) and chemokine (eotaxin) have been implicated in the promotion of allergic responses in asthma." (PMID 27741312, 2016). "Th2 cells are the central players in allergic asthma, as they are major producers of the type 2 cytokines interleukin-4 (IL-4), IL-5, and IL-13, which are all tightly linked to the pathogenesis of asthma." (PMID 26965110, 2016). "The majority of children who produced IL‐5 (in classes 4 and 5) had accompanying high‐level expression of IL‐13 (relative to Class 3), and high levels of IL‐5 were associated with high prevalence of asthma, wheeze and mite sensitization (classes 4 and 5)." (PMID 26061524, 2015). "Th2-type cytokines IL-4, IL-5, and IL-13 have been implicated in promoting allergic responses in asthma." (PMID 26110056, 2015). "Inhaled corticosteroids, which are the cornerstone of asthma treatment, cause eosinophil apoptosis by suppressing the synthesis of important eosinophil survival factors such as IL-3, IL-5, and GM-CSF." (PMID 25878402, 2015). "From age 3 years HDM-specific IL-5 and IL-13 responses were associated with atopy and asthma at the age of 8 years." (PMID 24875149, 2014). "Allergen-specific IL-5 responses at 8 years were strongly associated with the presence of asthma, eczema, atopy to any allergen and HDM-specific atopic responses, at this age." (PMID 24875149, 2014).
asthma (continued). "Over-expression of IL-4 leads to eosinophilia and mucus metaplasia as well as subepithelial fibrosis, whereas IL-5 over-expression is thought to result in an increased number of eosinophils in the airway, which is the hallmark of asthma." (PMID 24886260, 2014). "In the multivariate analysis, HDM-specific IL-5 responses at age 3, 5 and 8 years were each significantly associated with the presence of atopy and asthma at age 8 years." (PMID 24875149, 2014). "When these responses were corrected for the responses of other cytokines in a multivariate model, only the HDM-specific IL-5 responses were significantly and independently associated with atopy and asthma at 8 years." (PMID 24875149, 2014). "HDM-specific IL-5 responses at 3 years, 5 years and 8 years were significantly associated with the presence of asthma and atopy at 8 years." (PMID 24875149, 2014). "After adjusting for the effect of other cytokine responses, sex and intervention groups, HDM-specific IL-5 responses at 5 years were still significantly associated with asthma at 8 years." (PMID 24875149, 2014). "There is evidence that markers such as interleukin-5 and SE-IgE within the nasal polyp tissue are associated with co-morbid asthma, supporting the idea of a systemic immunologic cross talk)." (PMID 25379119, 2014). "We have shown significant univariate associations between HDM-specific IL-5 and IL-13 responses at age 3 years, 5 years and 8 years and the presence of asthma and atopy at 8 years." (PMID 24875149, 2014). "Although Th2 molecules such as IL-4, IL-5, and IL-13 are key cytokines involved in the inflammatory response in asthma, IFN-γ has also been associated with asthma severity." (PMID 22934153, 2012). "A recent study showed that the excessive production of interleukin (IL)-4, IL-5, and IL-13 by T-helper type 2 (Th2) cells is implicated in the development of asthma." (PMID 22203879, 2012). "The chromosome 5q31 locus which has been linked to blood P. falciparum parasites density also contains the genes encoding the cytokines IL-4, IL-5, and IL-13, and these have been associated with inflammatory diseases including asthma." (PMID 22216286, 2011). "To further corroborate these negative results, we used mice with genetic deficiency in IL-5 (il5-/-), a critical mediator of asthma which was consistently up-regulated in the airspace compartment of mice treated with ovalbumin." (PMID 20796309, 2010). "In asthma we found a positive association of IL-4 with IL-5, and significant association with IL-13, TNF α as well as GM-CSF, while IL-5 is positively associated with IL-4, IL-10 and GM-CSF." (PMID 20616938, 2010). "We found that there is a strong association of IL-4 cytokines with IL-5 in most of cases of allergic rhinitis, asthma, urticaria as well in patients showing skin and rhinitis." (PMID 20616938, 2010). "If the resultant inflammatory response is T helper-2 dominant, cytokine mediators typically associated with asthma [interleukin (IL)-4, IL-5, IL-9, IL-13] would subsequently be produced." (PMID 20064771, 2010). "But, classifying the number of asthma attacks occurring in the last year to categories from one to four, revealed that frequent asthma attacks in children are associated with higher IL-5 serum levels (p = 0.013)." (PMID 21179211, 2010). "In summary, PT, CR and their combinational prescription have deep inhibitory effects on airway inflammation in a murine model of asthma and it was caused by suppression of Th2 cytokines (IL-4, IL-5, IL-13), IgE, eosinophil CCR3 expression in lung." (PMID 19657453, 2009). "Moreover, interleukin (IL)-4, IL-5, and IL-13 represent key cytokines implicated in the progression of asthma." (PMID 40723867, 2025). "The increased understanding of such complex inflammatory pathways has resulted in the development of antibody-based biological therapies that target T2 cytokines such as IL-4, IL-5, and IL-13, which play key roles in the inflammatory processes underlying asthma." (PMID 41440490, 2025).